LINC02057 (long independently transcribed non-coding RNA 2057)
Gene: Long non-coding RNA gene on chromosome 5 (61,194,314 to 61,305,191, reverse strand). Ensembl gene ENSG00000249279.
Diseases named in the same sentence as LINC02057 in open-access papers:
LINC02057 is named in the same sentence as 1 disease in open-access papers, as found by Europe PMC text mining. Sharing a sentence is not in itself a finding about the gene and the disease. The quoted sentences say what the papers report.
tumor (1 paper, 2025). "The expression levels of AL590428.1, LINC02057, AC245041.1, AC068228.1, and AL365181.2 were verified using qRT-PCR in 16 tumor samples alongside paired normal samples." (PMID 40629658, 2025).